LINC-ROR (long independently transcribed non-coding RNA, regulator of reprogramming)
Diseases named in the same sentence as LINC-ROR in open-access papers (continued):
Sharing a sentence is not in itself a finding about the gene and the disease.
tumor (continued). "Quantitative realtime-PCR(qRT-PCR) analysis demonstrated that linc-ROR expression was up-regulated in tumor tissues compared with para-tumor tissues." (PMID 28580169, 2017). "High linc-ROR expression is thought to enhance tumor growth, migration and invasion, promote EMT, and/or influence the characteristics of cancer stem cells." (PMID 29050257, 2017). "Mechanistically, we found that linc-ROR functioned as a competing endogenous RNA (ceRNA) to several tumor suppressor microRNAs, particularly some members of let-7 family." (PMID 28580169, 2017). "Increasing evidence indicate that linc-ROR also plays a role in tumorigenesis and tumor progression; in most cases, it acts as an oncogene in cancers." (PMID 29237490, 2017). "Additional studies have indicated that linc-ROR regulates tumor stem cell differentiation, and promotes tumor cell proliferation, invasion and metastasis by regulating Oct4, Sox2, and Nanog expression via interfering with micro RNA-145." (PMID 29050257, 2017). "Additionally, the levels of β-catenin, WNT2B, and WNT10A were elevated in tumor specimens derived from lincROR overexpression group." (PMID 39546475, 2024). "Notably, LINC-ROR demonstrated potential ceRNA activity targeting other tumor-suppressor miRNAs, including miR-205, miR-181a, miR-99b, and let-7a-5p, reducing their effective concentrations, and protect core transcription factors in CSCs." (PMID 39170516, 2024). "In addition, linc-ROR is reported as a ceRNA for miR-145, therefore exerting a drug-resistance role in tumor cells of various types of cancer." (PMID 36827545, 2023). "Intriguingly, a few studies have positioned linc-ROR as a tumor-suppressor lncRNA, proposing it could be involved in several mechanistic pathways exerting multiple and even opposite functions." (PMID 36827545, 2023). "However, GC patients with underexpression of LINC-ROR were prone to N1/N2 steps of lymph node metastasis (47.1%), indicating that metastasis of tumor cells to the lymph node was declined via decreasing in LINC-ROR expression." (PMID 33745265, 2021). "Interestingly, the expression level of LINC-ROR decreased in tumor specimens with a low level of SALL4 expression (p < 0.05) compared to SALL4 overexpression samples (p = 0.92)." (PMID 33745265, 2021). "Interestingly, the over-expression of Linc-ROR has also been emphasized in undifferentiated tumors, with studies suggesting the existence of a strong correlation with tumor recurrence and poor response to treatment." (PMID 34447693, 2021). "However, the relationship between linc-ROR and the Wnt/β-catenin signaling pathway required deeper study in tumor initiation and progression." (PMID 32850817, 2020). "Linc-RoR was first reported to be overexpressed in OSCC tumor specimens." (PMID 31133028, 2019). "Many studies have shown the importance of linc-ROR as a tumor marker." (PMID 29596364, 2018). "However, the molecules that act as mechanisms that mediate linc-ROR’s effects must still be clearly identified before linc-ROR can be used in tumor treatment." (PMID 29596364, 2018). "This suggests that a high level of linc-ROR can promote tumor growth." (PMID 29050257, 2017). "Furthermore, we found that let-7, miR-7 and miR-451, which have been known to have key roles in repressing tumor proliferation, invasion and CSLCs properties, were ceRNA targets of linc-ROR." (PMID 28580169, 2017). "Moreover, linc-ROR disruption was sufficient to attenuate tumor growth and cancer stem cell marker expression in vivo." (PMID 29237490, 2017). "The effect of linc-ROR depletion on tumor growth was assessed by xenograft assay." (PMID 29237490, 2017). "Consistently, the results of our study revealed that FOXM1 could upregulate the expression of Linc-ROR in HNSCC cells, while the knockdown of Linc-ROR was shown to normalize the stimulatory effect associated with FOXM1 on tumor growth in the xenograft model of HNSCC cells." (PMID 34447693, 2021).
tumor (continued). "Therefore, Curcumin suppressed tumor growth through a lincROR/β-catenin regulatory pattern." (PMID 32714183, 2020). "Notably, increasing studies showed that linc-ROR could be used as a ceRNA, thus exerting its impact in the post-transcriptional network of tumor pathogenesis." (PMID 32850817, 2020). "Therefore, aberrant expression of linc-ROR may serve as a novel mechanism underlying SOX9 deregulation, and the linc-ROR–miRNA–SOX9 regulatory network provides a novel vision to understand the oncogenic and tumor suppressor network puzzle." (PMID 29237490, 2017). "Interestingly, linc-ROR was detected in extracellular vesicles released by tumor cells during hypoxia, suggesting that this lncRNA may contribute to the intercellular signaling promoting cell survival in hypoxic stress." (PMID 26131450, 2015). "In the current study, we demonstrated that lincROR was upregulated in most CRC cell lines and mediated CRC cell proliferation and tumor growth in vitro and in vivo." (PMID 39546475, 2024). "LMO4 has been reported to perform as a facilitator of tumor development by means activating the AKT/PI3K pathway, and moreover, LMO4 was reported as a target gene of Linc-ROR." (PMID 34447693, 2021). "Our findings revealed that the co-expression of LINC-ROR and SALL4 was significantly correlated with each other in the early steps of tumor development in patients." (PMID 33745265, 2021). "To further elucidate the mechanism of Linc-ROR regulating cell growth in HNSCC in vivo, we downregulated Linc-ROR and upregulated FOXM1 in TSCCA cells, and examined tumor growth by subcutaneous tumor formation assay." (PMID 34447693, 2021). "The expression of FOXM1 was increased while that of Linc-ROR, LMO4, and Ki-67 was decreased in the tumor tissue of the mice in the oe-FOXM1 + sh-Linc-ROR group when compared with the oe-FOXM1 group." (PMID 34447693, 2021). "Linc-ROR was most expressed in G3 tumours and MALAT1 expression, which was downregulated in tumour tissue, declined with tumour grade and reached the minimum in G3 tumours." (PMID 30205577, 2018). "We compared the expression levels of nine hypoxia-related lncRNAs39, 40, 41 (H19, HOTAIR, NEAT1, linc-ROR, UCA1, WT1, HINCUT1, LINK-A, LincRNA-p21) between tumor central and peripheral cells." (PMID 29106390, 2018). "Expressions of linc-ROR and MALAT1 in TT varied significantly with different tumour grade (Kruskal-Wallis: p = 0.0348 and p = 0.0454)." (PMID 30205577, 2018). "LINC‐ROR was specifically identified as a prognostic marker in OSCC due to its statistical significance in undifferentiated OSCC, history of tobacco chewing or smoking, therapeutic response and tumor recurrence." (PMID 40256126, 2025). "The RT-qPCR, Western blot and IHC results indicated that overexpression of FOXM1 upregulated the expression of Linc-ROR, LMO4, and Ki-67, while silencing of Linc-ROR downregulated the expression of LMO4 and Ki-67 as well as unchanged FOXM1 expression in the tumor tissues." (PMID 34447693, 2021). "Considering the prognostic role of LINC-ROR, its function in tumor progression, and its correlation with stemness markers, a probable correlation may be existed between the expression of LINC-ROR and SALL4 in tumorigenesis." (PMID 33745265, 2021). "Moreover, co-expression of LINC-ROR and SALL4 in tumor samples was significantly correlated with moderately differentiated (p = 0.05)." (PMID 33745265, 2021). "Tumor suppressive lncRNAs (GAS5, MEG3, FER1L4 and LINC00672) and oncogenic lncRNAs (CCAT2, BANCR, NEAT1, MALAT1, H19, Linc-RoR, TUG1, TDRG1 and PCGEM1) may be a few such examples." (PMID 30781521, 2019).
tumor (continued). "+, upregulated linc-ROR in tumor compared with non-tumor counterpart; –, linc-ROR downregulation in tumor." (PMID 29237490, 2017). "Therefore, linc-ROR appears to play a role in EMT programs, which promotes the invasive and metastatic abilities of tumor cells." (PMID 29050257, 2017). "Interestingly, a significant positive correlation was observed between the relative expression of linc-ROR and SOX9 in ESCC samples when compared to their matched non-tumor tissues (r = 0.562, P = 0.036)." (PMID 29237490, 2017). "Besides, linc-ROR might mediate TGFβ-dependent chemoresistance in HCC, as TGFβ-increased expression of CD133+ tumor-initiating cells and colony growth were attenuated by linc-ROR knockdown." (PMID 37781691, 2023). "There were also significant correlations between concomitant mRNA expression of SALL4 and LINC-ROR in tumors located at distal noncardiac, positive for H.pylori infection, tumors with invasion into the muscle layer of the stomach, and grade II tumor (p < 0.05)." (PMID 33745265, 2021). "However, our results propose that concomitant dysregulation of LINC-ROR and SALL4 in transcript level may have a potential role in tumor initiation and invasion of GC." (PMID 33745265, 2021). "Moreover, LINC-ROR silencing results in the inhibition of cell proliferation, invasion, and EMT through reducing CDH1 expression and increasing the expression of ZEB1/2 and Vimentin in ESCC tumor tissues." (PMID 33745265, 2021). "Moreover, we indicated a significant correlation between concomitant expression of LINC-ROR and stemness transcriptional factor SALL4 with clinicopathological features, including H. pylori infection, depth of tumor invasion, tumor location, differentiation, tumor grade, and sex in gastric tissues." (PMID 33745265, 2021). "Therefore, we aimed in the current study to evaluate the expression of LINC-ROR in tumor and adjacent non-cancerous tissues of GC patients and to investigate its probable linkage with SALL4 stemness regulator, as well as their correlation with clinicopathological features of patients." (PMID 33745265, 2021). "Amongst them, TUG1 and linc-ROR were not detectable in plasma, ZFAS1 was significantly up-regulated in plasma of tumor patients, while GAS5 showed no significant changes." (PMID 29559565, 2018). "A comparison of expression in tumour tissue (TT) and non-malignant mucosa tissue (MT) showed significant upregulation of CCAT1 and linc-ROR in TT (p < 0.001 and p = 0.001, respectively) and downregulation of ANRIL, MIR155HG and MALAT1 (p = 0.001, p = 0.010, p = 0.001, respectively)." (PMID 30205577, 2018).
cancer (56 papers, 2016 to 2025). A tumor composed of atypical neoplastic, often pleomorphic cells that invade other tissues. "Increasing documentation suggests that linc-ROR, a long intergenic non-coding RNA, is implicated in cancer proliferation, metastasis, and drug resistance." (PMID 36827545, 2023). "Increasing evidence has shown that the linc-ROR was abnormal expression in many cancers, and its dysregulation was associated with cellular functions." (PMID 32850817, 2020). "In general, linc-ROR can be easily associated with cell proliferation, differentiation, apoptosis, invasion, and metastasis in many human cancers." (PMID 29596364, 2018). "The oncogenic function of linc-ROR has been linked to the regulation of multiple signaling pathways, which are presumably important for the development and progression of cancers." (PMID 30250400, 2018). "Cisplatin resistance has been associated with linc-ROR upregulation in cancer cells." (PMID 36827545, 2023). "In addition, increasing evidence have shown that the abnormal expression of linc-ROR in various cancers was closely linked to tumorigenesis, diagnosis, metastasis, and prognosis through some signaling pathways." (PMID 32850817, 2020). "Interestingly, studies have shown that linc-ROR is not only closely associated with multiple biological functions of cancer cells but may also be an ideal and convenient biomarker." (PMID 32850817, 2020). "LincROR has been reported to be upregulated and to act as an oncogene in several cancers, we therefore examined its expression in a panel of CRC cell lines." (PMID 39546475, 2024). "Given the emerging applications of MEG3 and linc-ROR in cancer biology, further access to their co-expression patterns is needed to better understand their regulatory roles and synergistic effects in CRC cells." (PMID 39108882, 2024). "On this matter, this review aims to contribute to the current comprehension of linc-ROR and its implication in cancer proliferation, metastasis, and drug resistance." (PMID 36827545, 2023). "In this regard, many efforts have been made to establish the role of linc-ROR in cancer proliferation and progression." (PMID 36827545, 2023). "Although the properties of linc-ROR in relation to some cancers have been reviewed in the past, active research appends evidence constantly to a better comprehension of the role of linc-ROR in different stages of cancer." (PMID 36827545, 2023). "LincRoR has been shown to modulate cancer progression via interaction with microRNA-145, and microRNA-145-5p was shown to ameliorate hypertrophic scar through suppression of myofibroblast activation and reduction of Smad2/3." (PMID 36986051, 2023). "This review provides current synthesized information on linc-ROR molecular behavior, and portrays the clinical relevance known to date in an effort to elucidate further mechanisms to help improve cancer molecular behavior." (PMID 36827545, 2023). "LINC-ROR, as a cancer-related lncRNA, has vital roles in stem cell survival, pluripotency, differentiation, and self-renewal in hESCs." (PMID 33745265, 2021). "First, linc-ROR has been reported to directly affect the progression of various cancers through several signaling pathways." (PMID 32850817, 2020).
cancer (continued). "Of note, a number of studies have confirmed that linc-ROR can be considered as a possible new target for cancer therapy and a biomarker for cancer diagnosis." (PMID 32850817, 2020). "As a result, the expression level of linc-ROR in GC tissues was much lower than that in the corresponding adjacent cancer tissues." (PMID 33163123, 2020). "As such, the functional role of linc-ROR in cancer needs to be further explored and verified, especially in clinical applications." (PMID 32850817, 2020). "In this mini-review, we summarized the recent understanding of the molecular mechanisms of PKM2-associated LncRNAs, including MAFG-AS1, HULC, FEZF1-AS1, LincRNA-p21, MEG3, HOXB-AS3, TP53TG1 and Linc-ROR in cancer metabolism." (PMID 31654067, 2019). "Through searching the published literatures, six lncRNAs (ZFAS1, PRNCR1, GAS5, TUG1, linc-ROR, H19) which have been reported to be abnormally expressed in cancer were included in the present study." (PMID 29559565, 2018). "Although linc-ROR is over-expressed in various cancers, the target genes are variable and depend on the cell type." (PMID 29596364, 2018). "When si-ROR were transfected into the cancer cells to suppress the expression of linc-ROR, the growth of the tumors formed from the injected cells was apparently slower during the 1-month measurement period." (PMID 30250400, 2018). "Linc-ROR, a 2604bp lncRNA located on 18q21.31, was initially identified in pluripotent and embryonic stem cells and has been shown to be dysregulated in patients with various disorders, including cancer." (PMID 39925803, 2025). "linc-ROR plays a key role in the development and metastasis of malignant tumors including PC." (PMID 39408810, 2024). "On the other hand, linc-ROR has been identified as an oncogene that is upregulated in various types of cancer, exerting regulatory effects on proliferation, invasion, angiogenesis, and cancer stem cell pathways." (PMID 39108882, 2024). "The involvement of linc-ROR in cancer proliferation and metastasis has been documented, suggesting an important role in the clinicopathological characteristics of tumors, therefore considered an oncogene that affects prognosis, survival rate, and higher recurrence rate." (PMID 36827545, 2023). "Numerous studies have reported that dysregulated expression of LINC-ROR in CC contributes to cancer cell viability, proliferation, invasion, and/or metastasis and functions as competing endogenous RNA by sponging microRNA-145 and miRNA-223-3p or regulating the miR-6833-3p/SMC4 pathway." (PMID 35454158, 2022). "Additionally, linc-RoR acts as a ceRNA to the let-7 miRNA family and induces the properties of cancer stem-like cells." (PMID 34820419, 2021). "Overexpression of LINC-ROR was significantly related to the advanced stages of malignancies, metastasis to lymph nodes, and vascular invasion, suggesting that LINC-ROR could serve as a prognostic marker in some human cancers." (PMID 33745265, 2021). "Linc-RoR works as an oncogene in several cancers, enhances the cellular tolerance to hypoxic stress by acting as a miRNA sponge to miR-145, and promotes chemoresistance to anti-cancer drugs by inducing stem cell-like properties, as shown in HCC." (PMID 34820419, 2021). "As such, the expression of linc-ROR, which plays an important role in cancer prevention, diagnosis, and treatment may be increased through the administration of exosomal linc-ROR." (PMID 32850817, 2020). "A growing understanding of the role of linc-ROR in all types of cancers may opened up the possibility for many new treatment strategies." (PMID 32850817, 2020).